CENPK (centromere protein K)
Description:
Component of the CENPA-CAD (nucleosome distal) complex, a complex recruited to centromeres which is involved in assembly of kinetochore proteins, mitotic progression and chromosome segregation. May be involved in incorporation of newly synthesized CENPA into centromeres via its interaction with the CENPA-NAC complex. Acts in coordination with KNL1 to recruit the NDC80 complex to the outer kinetochore.
Synonyms: CENP-K; FKSG14; SOLT; AF5alpha; P33
Tractability: PROTAC: ubiquitination databases record sites on it.
Gene: Protein-coding gene on chromosome 5 (65,517,766 to 65,563,183, reverse strand). Ensembl gene ENSG00000123219.
Subcellular location: Nucleus; Chromosome, centromere; Chromosome, centromere, kinetochore
Pathways (Reactome):
Cell Cycle: Amplification of signal from unattached kinetochores via a MAD2 inhibitory signal; Deposition of new CENPA-containing nucleosomes at the centromere; EML4 and NUDC in mitotic spindle formation; Mitotic Prometaphase; Resolution of Sister Chromatid Cohesion; Separation of Sister Chromatids
Signal Transduction: RHO GTPases Activate Formins
Gene Ontology:
Molecular function: protein binding
Biological process: chromosome segregation; mitotic sister chromatid segregation; kinetochore assembly
Cellular component: inner kinetochore; cytosol; nucleoplasm; nucleus; chromosome, centromeric region
Genetic constraint (gnomAD): Loss-of-function variants: 8 observed, 8.53 expected, observed/expected ratio (o/e) 0.94, 90% interval 0.55 to 1.64. That is too few expected variants to judge how well the gene tolerates losing a copy. Missense variants: 97 observed, 94.94 expected, observed/expected ratio (o/e) 1.02, 90% interval 0.87 to 1.21. Synonymous variants: 31 observed, 32.52 expected, observed/expected ratio (o/e) 0.95, 90% interval 0.71 to 1.29.
Homologues: Orthologues: chimpanzee CENPK (99% identical), macaque CENPK (97% identical), pig CENPK (87% identical), rabbit CENPK (86% identical), guinea pig CENPK (85% identical), dog CENPK (81% identical), rat Cenpk (77% identical), mouse Cenpk (75% identical), tropical clawed frog cenpk (56% identical), zebrafish cenpk (38% identical).
Diseases named in the same sentence as CENPK in open-access papers:
CENPK is named in the same sentence as 28 diseases in open-access papers, as found by Europe PMC text mining. Sharing a sentence is not in itself a finding about the gene and the disease. The quoted sentences say what the papers report.
cervical cancer (9 papers, 2022 to 2025). A primary or metastatic malignant neoplasm involving the cervix. "Elevated expression of m6A-modified CENPK in cervical cancer was associated with cancer recurrence and independently predicted poor prognosis." (PMID 38655053, 2024). "For example, elevated CENPK expression in cervical cancer was associated with cancer recurrence and independently predicted poor patient prognosis." (PMID 37042849, 2023). "Subsequent GSVA revealed that pathways involving CENPK had the greatest overlap with m6A-modified clusters associated with cervical cancer." (PMID 35418160, 2022). "CENPK expression was elevated in cervical cancer, associated with cancer recurrence, and independently predicts poor patient prognosis [hazard ratio = 1.413, 95% confidence interval = 1.078 − 1.853, P = 0.012]." (PMID 35418160, 2022). "Based on the association between dysregulation of m6A methylation and cervical cancer, we were able to identify CENPK as a primary target of m6A RNA methylation that was also correlated with cancer development." (PMID 35418160, 2022). "And, ZC3H13 can mediate m6A modification of centromere protein K (CENPK) to promote the progression of cervical cancer." (PMID 41256854, 2025). "A few recent studies have reported that CENPK played roles in cervical cancer, thyroid cancer, ovarian cancer, etc.." (PMID 37938151, 2023). "Given this validation of CENPK contribution to cervical cancer, we sought to determine how CENPK affected cell stemness, chemoresistance, metastasis, and proliferation." (PMID 35418160, 2022). "To further establish the central role of CENPK in cervical cancer, we conducted IHC analysis of 119 cervical cancer samples and 35 adjacent normal tissues." (PMID 35418160, 2022). "In contrast, CENPK downregulation resulted in delayed progression of cervical cancer in vitro and in vivo." (PMID 35418160, 2022). "Silencing of CENPK prolonged the overall survival time of cervical cancer-bearing mice and improved the response of cervical cancer tumors to chemotherapy in vivo (P < 0.001)." (PMID 35418160, 2022). "We established cervical cancer models in BALB/c-nu mice harboring wild-type or stably-silenced CENPK to determine how CENPK affected cancer progression in vivo." (PMID 35418160, 2022). "The roles of m6A RNA methylation and centromere protein K (CENPK) in cervical cancer were analyzed using bioinformatics analysis." (PMID 35418160, 2022). "This work thus demonstrated a role for m6A RNA methylation in controlling specific signaling pathways and highlighted a theoretic framework for clinical application of CENPK as a prognostic indicator and as a novel target for cervical cancer treatments." (PMID 35418160, 2022). "CENPK was shown to have an oncogenic role in cervical cancer and can thus serve as a prognostic indicator and novel target for cervical cancer treatment." (PMID 35418160, 2022). "Quantitative analysis of IHC staining, followed by univariate and multivariate COX hazard analyses, indicated that CENPK expression was an independent and unfavorable prognostic indicator for overall and recurrence-free survival in cervical cancer patients." (PMID 35418160, 2022). "Taken together, these results indicated a strong correlation between CENPK expression and the dysregulation of m6A modifications in cervical cancer." (PMID 35418160, 2022). "Because CENPK expression was correlated with cancer recurrence, we further investigated the relationship between CENPK expression and recurrence-free survival in cervical cancer patients." (PMID 35418160, 2022). "Survival analysis suggested that cervical cancer patients with high CENPK expression exhibited poor overall survival." (PMID 35418160, 2022).
cervical cancer (continued). "Our findings further illustrated how ZC3H13 functions in promoting the tumorigenic properties of cervical cancer cells via CENPK." (PMID 35418160, 2022). "Survival analysis of cervical cancer patients confirmed that high CENPK expression was a predictor of poor recurrence-free survival, which is consistent with correlation analysis." (PMID 35418160, 2022). "Taken together, these data showed a clear role for CENPK in cervical cancer development and indicated the clinical value as a potential biomarker." (PMID 35418160, 2022). "The results showed elevation of CENPK expression in cervical cancer compared with adjacent normal tissues." (PMID 35418160, 2022). "Recent papers report that wild-type CENPK contributes to the malignant progression, boosts proliferation and migration in gastric cancer, and predicts the prognosis of prostate cancer as well as cervical cancer." (PMID 39404386, 2024). "Notably, m6A-modified CENPK RNA exhibits high expression and is positively correlated with the overall and recurrence-free survival rates of cervical cancer patients." (PMID 39155349, 2024). "Moreover, immunofluorescence staining of γ-H2AX (Ser139) showed that downregulation of CENPK led to enhanced DNA damage in cervical cancer cells treated with platinum-based drugs." (PMID 35418160, 2022). "ZC3H13 enhanced stemness and chemoresistance via modulation of CENPK mRNA in cervical cancer cells." (PMID 36091006, 2022). "Moreover, high CENPK expression was positively correlated with poor overall and recurrence-free survival in cervical cancer patients." (PMID 35418160, 2022). "Despite this broad contribution to different cancers, the relationship between CENPK and cervical cancer remains unknown, and the mechanism by which CENPK dysregulates cancer progression has not been established." (PMID 35418160, 2022). "Because CENPK has a potential oncogenic role in cervical cancer, we speculated that ZC3H13 might be responsible for m6A methylation of CENPK mRNA." (PMID 35418160, 2022). "Indeed, tumorsphere and colony formation, and Transwell, EdU, and immunofluorescence staining assays showed that ZC3H13 knockdown had a suppressive effect on cervical cancer stemness, chemoresistance, metastasis, and cell proliferation that was reversed by ov-CENPK in HeLa and SiHa cells." (PMID 35418160, 2022). "Tumorsphere formation assays and immunofluorescence staining of cervical cancer stem cell markers (CD133 and CD44) indicated that CENPK knockdown reduced stemness of HeLa and SiHa cells." (PMID 35418160, 2022). "Bioinformatics analysis of public cancer datasets revealed firm links between m6A modification patterns and cervical cancer prognosis, especially through ZC3H13-mediated m6A modification of CENPK mRNA." (PMID 35418160, 2022). "Moreover, we confirmed that ZC3H13 enhanced CENPK expression, supporting the bioinformatic findings of m6A-mediated dysregulation of CENPK and the correlation between ZC3H13 and CENPK in cervical cancer." (PMID 35418160, 2022).
ovarian carcinoma (9 papers, 2015 to 2024). A malignant neoplasm originating from the surface ovarian epithelium. "CENPK, a member of the centromeric protein family, was markedly upregulated in ovarian cancer tissues and associated with poor prognosis in patients." (PMID 30793530, 2019). "Second, RNAi-mediated CENPK knockdown caused a significant decrease in the growth rate of ovarian cancer cells, which implies that CENPK has an oncogenic role." (PMID 26587348, 2015). "Third, high expression of CENPK by clinical ovarian tumors was associated with a shorter survival of ovarian cancer patients." (PMID 26587348, 2015). "We identified that CENPK is specifically upregulated in ovarian cancer cells, and its overexpression is associated with a poor prognosis in patients with ovarian cancer." (PMID 26587348, 2015). "In this study, we revealed for the first time that CENPK was overexpressed in ovarian cancer cell lines and tissues and its overexpression was associated with poor outcomes of ovarian cancer." (PMID 26587348, 2015). "Likewise, CENPK is a kinetochore protein and its overexpression in hepatocellular carcinoma promotes proliferation and in ovarian cancer is associated with a poor prognosis." (PMID 39202425, 2024). "In this study for the first time, we identified a member of the centromere protein (CENP) family, CENPK, which was specifically upregulated in ovarian cancer tissues and cell lines and the overexpression of which was associated with poor prognoses in patients with ovarian cancer." (PMID 26587348, 2015). "Previous studies have suggested links between centromere protein K (CENPK) and the progression of malignant tumors, such as ovarian cancer, breast cancer, hepatocellular carcinoma, bladder cancer, oligodendrogliomas, and lung adenocarcinoma." (PMID 35418160, 2022). "It was previously documented that CENPK aggravated the development of hepatocellular carcinoma and ovarian cancer." (PMID 34044826, 2021). "Overexpression of CENPK has been demonstrated in various human malignancies including hepatocellular carcinoma, ovarian cancer, and breast cancer." (PMID 33478508, 2021). "For example, CENPK was shown to be upregulated in ovarian cancer and its upregulation was related to poor prognosis." (PMID 33478508, 2021). "Next, we analyzed the prognostic relevance of CENPK in ovarian cancer using a Kaplan–Meier survival analysis." (PMID 26587348, 2015). "We observed that CENPK expression was significantly upregulated in ovarian cancer tissues compared to a normal group." (PMID 26587348, 2015). "To understand the roles of CENPK in ovarian cancer, we first analyzed expression levels of CENPK mRNA in three normal cell lines and three ovarian cancer cell lines by a quantitative RT-PCR." (PMID 26587348, 2015). "We analyzed CENPK gene expression level with respect to ovarian cancer in 53 subjects with stage III/IV grade 3 serous ovarian carcinoma, and survival analysis was censored by survival months." (PMID 26587348, 2015). "Collectively, this study is the first to report that CENPK is upregulated in ovarian cancer tissues and cell lines and also showed that high CENPK expression in ovarian tumors is a strong predictor of a poor prognosis." (PMID 26587348, 2015). "Compared to three non-tumorigenic cell lines (H184B5H5/M10, T/G HA-VSMC, and HFL1), CENPK mRNA was highly expressed in ovarian cancer cell lines, including TOV-21G, OC314, and TOV-112D." (PMID 26587348, 2015). "First, among CENP family proteins, CENPK was specifically upregulated in ovarian cancer tissues and cell lines." (PMID 26587348, 2015). "Taken together, these results indicate that CENPK plays an oncogenic role, and RNAi directed against CENPK significantly decreased the growth rate of ovarian cancer cells." (PMID 26587348, 2015). "In conclusion, we identified that CENPK was specifically upregulated in ovarian cancer cells and can be used as a novel tumor marker of ovarian cancer." (PMID 26587348, 2015).
ovarian carcinoma (continued). "Collectively, in the present study, we show that the presence of CENPK can significantly improve the sensitivity of CA125 or HE4 for predicting clinical outcomes of ovarian cancer patients." (PMID 26587348, 2015). "In this study for the first time, we identified the important role played by a member of the CENP family proteins, CENPK, as a novel tumor marker of ovarian cancer." (PMID 26587348, 2015). "Fourth, CENPK can complement CA125 or HE4 to significantly improve the sensitivity of clinical outcomes of ovarian cancer patients." (PMID 26587348, 2015). "Previous studies have shown that CENPK is abnormally up-regulated in a variety of tumor tissues and cells, and has been used as a new tumor marker in a variety of cancers such as hepatocellular carcinoma and ovarian cancer." (PMID 37370088, 2023). "In addition, the presence of CENPK significantly improved the sensitivity of CA125 or HE4 for predicting clinical outcomes of ovarian cancer patients." (PMID 26587348, 2015). "Thus, we conclude that CENPK is a novel oncogene of ovarian cancer and located on amplified region of chromosome 5q11-14 in ovarian cancer." (PMID 26587348, 2015). "Further, to understand whether CENPK can complement CA125 or HE4 to improve the sensitivity of clinical outcomes of ovarian cancer patients, combinations of two- and three-gene models were analyzed using the Kaplan–Meier survival analysis." (PMID 26587348, 2015). "Previously, CENPK was identified as an oncogene that was overexpressed in hepatocellular carcinoma, ovarian cancer and triple‐negative breast cancer." (PMID 34382342, 2021). "Moreover, incorporating CENPK with the gold standard tumor markers, CA125 or HE4, can improve the sensitivity of CA125 or HE4 for predicting ovarian cancer outcomes." (PMID 26587348, 2015).
hepatocellular carcinoma (7 papers, 2017 to 2024). A malignant tumor that arises from hepatocytes. "Wang JL and coworkers suggested that the CENPK might participate in regulating malignant progression of hepatocellular carcinoma by CENPK–YAP1–EMT axis." (PMID 33904381, 2021).